NDRG2 (NDRG family member 2)
Diseases named in the same sentence as NDRG2 in open-access papers (continued):
Sharing a sentence is not in itself a finding about the gene and the disease.
tumor (continued). "Whereas these studies have clarified the function of NDRG2 in cancer cells and provided reasons as to why it is frequently downregulated in many cancers, its role in non-cancerous cells in the tumor microenvironment has so far remained elusive." (PMID 29463798, 2018). "NDRG2 is a member of the NDRG family, which consists of NDRG1, NDRG2, NDRG3 and NDRG4 and is located at chromosome 14q11.2, a region that has been reported to harbor a tumor suppressor gene." (PMID 28390436, 2017). "The comparison showed that the means of NDRG2 gene mRNA expression of hormones in invasive and non-invasive tumor groups were various." (PMID 28390436, 2017). "CD24 may be a downstream target of NDRG2 in cancer, and the combination of CD24 and NDRG2 is considered an effective biomarker of tumor behavior." (PMID 26506239, 2016). "Therefore, NDRG2 expression can increase the phosphorylation of p38 MAPK, which further inhibits the phosphorylation of SOCS1 and suppresses tumor proliferation." (PMID 26506239, 2016). "Ad-NDRG2, LEN-NDRG2, and B16F10-NDRG2 injections as well as other interventions that increase NDRG2 expression may control tumor progression." (PMID 26506239, 2016). "Although the contribution of NDRG2 to tumour homeostasis is complicated and not yet fully understood, our findings provide a better understanding of the energy metabolism of tumours." (PMID 24636131, 2014). "NDRG2 expression correlates with ESCC TNM stage, tumour differentiation and overall survival of ESCC patients, and up-regulating NDRG2 expression by adenovirus could inhibit the growth of ESCC cells in vitro and in vivo." (PMID 23800335, 2013). "According to RT-PCR results of the 185 tested cases, it was found that compared with normal tissues, 112 (60.78 %) tumor specimens showed no or low expression of NDRG2, while 73 (39.22 %) tumor tissues showed high expression of NDRG2." (PMID 23307246, 2013). "Again, the mRNA levels of both, FXR and NDRG2, were found to be reduced significantly in tumor tissue compared to normal liver tissue (data not shown)." (PMID 23056173, 2012). "Furthermore, publically available data from a genome wide gene expression study with matched “normal” and “tumor” tissues from 10 patients with HCC were retrieved and analyzed for FXR and NDRG2 mRNA levels." (PMID 23056173, 2012). "Although we observed a significant difference between normal and tumor tissues with regard to NDRG2 mRNA levels, we are aware that it is not a satisfying sample size to draw any conclusions from, but our data are consistent with recent findings by others." (PMID 21226903, 2011). "A comparison of the mean NDRG2 mRNA expression of primary tumours and that of their metastases to regional lymph nodes did not demonstrate any statistical differences (p > 0.05)." (PMID 20804549, 2010). "While human NDRG3 shares similarity to NDRG2 regarding its amino acid sequence and structure, the crystal structure of NDRG3 demonstrated considerable structural differences in a flexible loop analogous to helix α6 of NDRG2 that is thought to be involved in tumor suppression." (PMID 40378957, 2025). "However, like NDRG1, patients with aggressive tumor types such as ER– and basal-like tumors expressed higher levels of NDRG2 relative to those with ER+ tumors and non-basal subtypes (p < 0.0001)." (PMID 38611020, 2024). "Not only were their levels reduced in BC cells, but also the expression of NDRG2 was found to be negatively correlated with PD1 expression, suggesting that increasing NDRG2 expression could activate T-cell proliferation to counteract tumor invasion." (PMID 36685904, 2022). "Low effectiveness on various treatments in NDRG2-negative tumor patients may be resulted to the poor prognosis and low survival rates in these patients." (PMID 29348517, 2018).
tumor (continued). "They found that, although green fluorescent protein (GFP)-labeled TAMs could not be detected anymore at the end of the study, the presence of WT TAMs but not NDRG2-KO TAMs at tumor initiation was sufficient to increase tumor size." (PMID 29463798, 2018). "Additionally, the suppression effects of Ndrg2−/− macrophages were abolished by pretreating the macrophages with BAY-11-7082, which suggested that the NF-κB pathway plays a pivotal role in inducing the Ndrg2−/− macrophage tumor-suppressor phenotype." (PMID 29445150, 2018). "It was reported that the expression level of NDRG2 mRNA was very high in brain, salivary gland, skeletal muscle and mammary gland; low in bone marrow, testis, peripheral blood and placenta; and not detectable in leukocytes, colon and some tumour cell lines." (PMID 23800335, 2013). "Ectopic expression of FXR in SK-Hep1 cells reduced tumor growth and metastasis potential of corresponding cells and increased the anti-tumor efficacy of FXR agonists, which may be partly mediated via increased NDRG2 expression." (PMID 23056173, 2012). "In addition, increased frequency of NDRG2 down-regulation was observed in patients with elevated AFP serum level (P = 0.006), late TNM stage (P = 0.009), poor differentiation grade (P = 0.002), tumor invasion (P = 0.004) and recurrence (P = 0.024)." (PMID 21676268, 2011). "However, a Benjamini-Hochberg correction showed that none of the tissues showed a significant reduction in NDRG2 mRNA expression in tumor tissue compared to normal tissue." (PMID 21226903, 2011). "NDRG2 expression did not correlate with patient age, sex or tumor size." (PMID 21676268, 2011). "The Ad-NDRG2 group achieved a sustained and significant arrest of tumour growth (66.7% decrease in mean tumour volume on day 24 compared with the control group), whereas the growth of tumours injected with Ad-LacZ was not significantly inhibited (3.8% decrease compared with the control group)." (PMID 23800335, 2013). "Unlike NDRG1 and NDRG2, NDRG3 facilitates tumor progression and metastasis via activating the WNT/β-catenin pathway." (PMID 40378957, 2025). "A lack of NDRG2 in TAMs promotes M1 polarization, producing IL1, IL12, and TNFα, thereby inhibiting the tumor growth." (PMID 36572898, 2022). "At the end of the experiment (the 25th day), mice were euthanized and tumor tissues were excised, the weight and sizes of xenograft formed by SKOV3 cells with NDRG2 overexpression were clearly smaller than those formed by normal SKOV3 cells." (PMID 32345304, 2020). "The univariate analysis results showed that NDRG2 and LDHA protein levels are closely related to overall survival of HCC patients independent of age, gender, AFP, tumor size and HBsAg." (PMID 31523182, 2019). "The tumor size of HCC tissues from the patients undergoing hepatic resection is relatively moderate, and therefore not correlated closely with NDRG2 and LDHA expression." (PMID 31523182, 2019). "Our results showed that NDRG2 and LDHA expression correlated with histological differentiation, vascular invasion and TNM stage of HCC patients, but not correlated with tumor size of HCC patients." (PMID 31523182, 2019). "Besides, NDRG2 protection on photoreceptor cell viability might also be due to mechanisms such as maintained autophagy, for which certain NDRG is involved in the autophagic mammalian target of rapamycin (mTOR) signaling-determined tumor resistance toward alkylating chemotherapy." (PMID 30245855, 2018). "Another NDRG family protein, the Myc-repressed gene NDRG2, though not as extensively studied as NDRG1, has demonstrated tumor-suppressive functions in malignant carcinomas." (PMID 30591630, 2018). "Factors, such as age, sex, tumour stage in TNM system, were of no significance for NDRG2 mRNA expression level (p > 0.1)." (PMID 20804549, 2010).
tumor (continued). "Furthermore, a significant negative relationship was observed between NDRG2 and Edmondson's histological grade (P = 0.002), TNM stage (P = 0.009), invasive tumor features such as tumor recurrence (P = 0.024) and tumor invasion (P = 0.004)." (PMID 21676268, 2011).
cancer (76 papers, 2007 to 2025). A tumor composed of atypical neoplastic, often pleomorphic cells that invade other tissues. "NDRG2 increases the susceptibility to apoptosis in various physiological environments of cells, such as development, hypoxia, nutrient deprivation, and cancer drug treatment." (PMID 34685629, 2021). "The downregulation of N-Myc downstream-regulated gene 2 (NDRG2) is known to be associated with the progression and poor prognosis of several cancers." (PMID 29348517, 2018). "N-Myc downstream-regulated gene 2 (NDRG2) is associated with cell differentiation and proliferation in various cancers." (PMID 30544619, 2018). "Despite its role in cancer cells, the exact function of NDRG2 in the liver metastasis-associated microenvironment, especially in metastasis-associated macrophages, has not been investigated." (PMID 29445150, 2018). "NDRG2 down-regulation is associated with cancer development and progression, including such features as malignant clinical manifestations and increased pathological grade." (PMID 26506239, 2016). "The anti-cancer effect of NDRG2 is associated with many important signaling pathways in a variety of human cancers." (PMID 25061501, 2014). "N-myc Downstream Regulated Gene 2 (NDRG2) is a member of a recently identified gene family which has been implicated in human nervous system disorders and cancer." (PMID 17935612, 2007). "NDRG2 gene may be a promising target for cancer, because NDRG2 down-regulation is associated with cancer development and progression, including such features as malignant clinical manifestations and increased pathological grade." (PMID 28390436, 2017). "It is unknown whether cancer incidence and progression differs in people under chronic stress, which may contribute to a better understanding of the association between NDRG2 and cancer." (PMID 26506239, 2016). "This review focuses on the latest progress regarding the associations between NDRG2 and cancer." (PMID 26506239, 2016). "However, the associations between NDRG2 and cancer and the corresponding mechanistic details require intensive research." (PMID 26506239, 2016). "Further investigations considering transcriptional NDRG2 regulation and clinical significance in basal-type cancer are needed that may help to understand underlying pathways in more detail, finally helping to improve disease management." (PMID 27400234, 2016). "Previous studies demonstrated that NDGR2 expression in cancer cell lines could be enhanced by adriamycin, hypoxia and radiation, and that NDRG2 was implicated in regulation of adriamycin-induced apoptosis and radioresistance." (PMID 22920753, 2012). "Further studies are needed to address whether the down-regulation of NDRG2 is a cause or consequence of the progression from the normal thyroid tissue to a carcinoma." (PMID 18940011, 2008). "Therefore, should be further studies to show that NDRG2 up-regulation may be a promising therapeutic strategy for the treatment of cancer and that might be associated with PA development, as well." (PMID 28390436, 2017). "However, whether NDRG2 down-regulation is a cause or a consequence of the progression from normal tissue to carcinoma must be addressed." (PMID 26506239, 2016). "Both results illustrate the intricate regulatory networks that include CD36 and NDRG2, as well as their roles in regulating metabolic pathways and safeguarding against cancer." (PMID 38747892, 2024). "Further research is required to explore how these pathways contribute to the effectiveness of NDRG2 in treating malignant tumors." (PMID 37450923, 2024).
cancer (continued). "NDRG2, a tumor suppressor gene, has been shown to inhibit the growth and metastasis of many malignant tumors, including HCC, and its expression level is positively associated with the prognosis and survival outcomes of cancer patients." (PMID 38874512, 2024). "To confirm the relationship of cancer vulnerability between low NDRG2 expression and PRMT5/MEP50 activity, we used three recently developed potent and specific PRMT5 inhibitors (EPZ015866, CMP5, and HLCL61)." (PMID 38474089, 2024). "Treatment with the PRMT5-specific inhibitors CMP5 and HLCL61 was more sensitive in NDRG2low cancer cells than in NDRG2-expressing cells via the inhibition of HSP90 arginine methylation, along with the degradation of client proteins." (PMID 38474089, 2024). "In cancer cells, the transcription factor Myc causes overexpression of miRNA-186 and miR-9, which inhibit E-cadherin, as well as PRS-19, while inhibiting NDRG2 expression, ultimately leading to epithelial-mesenchymal transition (EMT) in the cancer cell." (PMID 38186581, 2023). "Most of the genes showed an increase in gene expression during the stages of cancer, particularly in the last two stages, except for NDRG2, FAM3D, KRT78, SLURP1, MUC21, and CRCT1, which showed a significant drop in gene expression compared to normal tissue." (PMID 37917867, 2023). "NDRG2 has been shown to inhibit the occurrence and metastasis of tumors and increase the sensitivity of anti-cancer drugs." (PMID 36849756, 2023). "Majority of the NRGs were deregulated in cancer tissues as compared to normal tissues which showed a uniform downregulated expression pattern except for NDRG2, BCL2, PRKN, TLR3, and STUB1." (PMID 36389725, 2022). "We used pan-cancer RNA-seq data from the UCSC XENA to evaluate the mRNA expression levels of NDRG1 and NDRG2 in diverse human cancers." (PMID 35795037, 2022). "In GC cells, it has been shown that overexpression of SENP2 desumoylates and stabilizes NDRG2, which results in inhibition of cancer cell proliferation." (PMID 35887358, 2022). "The combination of MDM2 knockdown and NDRG2 overexpression inhibits cancer cell proliferation and induces apoptosis in vitro and in the xeno-transplantation model." (PMID 34685629, 2021). "This review can assist the design of research regarding NDRG2 function and suggests the potential of NDRG2 as a molecular target for cancer patients." (PMID 34685629, 2021). "Despite its role in cancer cells, the effects of NDRG2 on PD-L1 expression and PD-L1-PD-1 pathway disruption have not been investigated." (PMID 34885221, 2021). "In contrast, NDRG2 overexpression in 4T1 cells decreased the suppressive effect of cancer cells on CD8+ T cell proliferation (with a 4T1 cell to splenocyte ratio of 1:10)." (PMID 34885221, 2021). "Since ASCT2 as a major glutamine transporter were found highly expressed in numerous cancers 31, 40, we thus would like to further confirm the reciprocal relationship between NDRG2 and ASCT2." (PMID 33162818, 2020). "In this study, results of the meta-analysis demonstrated that downregulation of NDRG2 was associated with poor OS (HR = 1.96, 95% CI: 1.60–2.40, P < .001) and DFS (HR = 2.70, 95% CI: 1.42–5.13, P = .002) in various types of cancers." (PMID 33031336, 2020). "As a member of the N-myc down-regulated gene family, N-Myc downstream-regulated gene 2 (NDRG2) contributes to the tumorigenesis of various types of cancers." (PMID 33031336, 2020). "All 13 included cohorts reported the results of OS toward NDRG2 expression with a total of 1980 cancer patients." (PMID 33031336, 2020). "The results demonstrated that low expression level of NDRG2 was correlated with poor OS in human cancer (HR = 1.96, 95% CI: 1.60–2.40, P < .001)." (PMID 33031336, 2020). "In adrenocortical carcinoma cells, miR-483-5p targets and suppresses NDRG2 to promote cancer invasion and pathogenesis." (PMID 31138100, 2019).
cancer (continued). "This miRNA regulation was proposed as a mechanism to help suppress NDRG2 expression in cancer cells along with epigenetic silencing." (PMID 31138100, 2019). "The N-myc downstream regulated gene 2 (NDRG2) is a tumor suppressor gene and is frequently lost in various types of cancer." (PMID 31523182, 2019). "One such example is the role of the Myc-repressed gene N-myc downstream-regulated gene 2 (NDRG2) in cancer." (PMID 29463798, 2018). "Series of studies have been done to explore the expression and the clinical significance of NDRG2 in cancers including hematological malignancies." (PMID 30348117, 2018). "Using BM transplantation together with macrophage and cancer cell mixed culture experiments, we confirmed that BMDMs were responsible for the suppression phenotype of the Ndrg2−/− liver microenvironment." (PMID 29445150, 2018). "Many studies followed in which NDRG2 was found to be downregulated in several types of cancers, an expression pattern that correlated with worse prognosis." (PMID 29463798, 2018). "Most importantly, through modulating the STAT3 and AKT pathways, NDRG2 can play an anti-cancer role downstream MYB/miR-130a in SACC." (PMID 30206227, 2018). "Recently, it has been demonstrated that NDRG2 plays a role in apoptosis induction, with a high number of apoptotic cells observed among NDRG2-expressed carcinoma cells compared with those among mock cells under metabolic stress or treatment anti-cancer drugs." (PMID 29348517, 2018). "NDRG2 is highly expressed in the brain and skeletal muscle, while it is marginally expressed or almost undetectable in the several human cancer cell lines." (PMID 28390436, 2017). "In line, a significant higher intensity of NDRG2 immunohistochemical staining was achieved in triple negative cancers in contrast to luminal-type and HER2-enriched specimens." (PMID 27400234, 2016). "In this review, we discuss the expression as well as the clinical and pathological significance of NDRG2 in cancer." (PMID 26506239, 2016). "The information compiled here comprehensively characterizes NDRG2 activity related to cancer, thus potentially aiding in the design of experimental research and promoting NDRG2 as a therapeutic target for cancer." (PMID 26506239, 2016). "First, the expression as well as the clinical and pathological significance of NDRG2 in cancer is introduced." (PMID 26506239, 2016). "NDRG2 expression is down-regulated in human cancer, and NDRG2 overexpression inhibits the proliferation, migration, metastasis and invasion of cancer cells." (PMID 26506239, 2016). "The information reviewed here should assist in experimental design and increase the potential of NDRG2 as a therapeutic target for cancer." (PMID 26506239, 2016). "NDRG1 and NDRG2 have been further shown to be iron chelator responsive genes in a number of cancer cell lines." (PMID 27589737, 2016). "To understand the role of NDRG2 in cancer and provide insight into its mechanisms of action and potential applications, we have focused on the molecular basis of NDRG2 activity in this section." (PMID 26506239, 2016). "The identification of the functions of NDRG2 provides a powerful tool to understand the molecular mechanism of cancer development under stress conditions and to develop clinical applications for cancer diagnosis and therapy." (PMID 26269411, 2015). "N-Myc downstream regulated gene 2 (NDRG2) is a tumor suppressor gene inhibiting cancer growth, metastasis and invasion." (PMID 26317652, 2015). "In this study, we discovered the role of the tumor suppressor gene NDRG2 in aerobic glycolysis and glutaminolysis of cancer cells." (PMID 26317652, 2015). "The frequency of Ndrg2 methylation in GC tissues and PCHNTs was significant higher than that in non-cancer control (P=0.000, and P<0.05, respectively)." (PMID 25823664, 2015).